YEATS4 (YEATS domain containing 4)
Diseases named in the same sentence as YEATS4 in open-access papers (continued):
Sharing a sentence is not in itself a finding about the gene and the disease.
bladder cancer (2 papers, 2024 to 2025). "We further investigated how YEATS4 is stabilized in bladder cancer at the posttranslational level, which may provide therapeutic opportunities." (PMID 38526153, 2024).
uterine fibroids (2 papers, 2023 to 2024). "It has been proved that patients with germinal mutation in the SRCAP members YEATS4 and ZNHIT1 predispose to uterine leiomyoma." (PMID 37466765, 2024).
depressive disorder (1 paper, 2017). A melancholy feeling of sadness and despair. "However, it remains unclear how YEATS4 is associated with depressive disorder." (PMID 28596527, 2017).
Hypertension (1 paper, 2020). The presence of chronic increased pressure in the systemic arterial system. "Unlike the ADRB2, PRKCA and WNK1 genes, there was no reference found in the literature that connects the YEATS4 gene with pathways associated with hypertension or drug response." (PMID 33316892, 2020). "Of note, the role of YEATS4 in the development of hypertension remains elusive, however, previous findings and observations made in this study suggest that polymorphism in this gene may predict blood pressure response to thiazide diuretics among patients of African ancestry." (PMID 33316892, 2020).
liver cancer (1 paper, 2023). An epithelial or non-epithelial malignant neoplasm that arises from the liver. "Moreover, YEATS4 can bind and activate transcriptional elongation factor A1 (TCEA1), which then promotes the upregulation of DDX3, a DEAD-box family RNA helicase with multiple cellular functions that plays an important role in liver cancer." (PMID 37435030, 2023).
Pleural effusion (1 paper, 2025). The presence of an excessive amount of fluid in the pleural cavity. "For pleural effusion, BL and EP tumor cells had higher expression of mitochondria-associated genes, such as CO (cytochrome C oxidase), ND (NADH dehydrogenase), and ATP6, while LP cells expressed EMT-associated genes, such as YEATS4, MDM2, and RGS5." (PMID 39955556, 2025).
cancer (20 papers, 2011 to 2025). A tumor composed of atypical neoplastic, often pleomorphic cells that invade other tissues. "YEATS4 amplification is detected in 3% of LSCC and 5% of LUAD from TCGA-pan cancer database 36 and GAS41 overexpression is also implicated in NSCLC4." (PMID 38514704, 2024). "Clinically, it is well-reported that the cancer genetics alternations of YEATS4 in NSCLC are most likely genomic amplification." (PMID 38514704, 2024). "The molecular mechanisms of YEATS4 in various cancers are also different, and similarities in molecular mechanisms or interactions in other cancers require further validation." (PMID 37435030, 2023). "This review comprehensively and extensively summarizes the functions, structure and oncogenic roles of YEATS4 in cancer progression and aims to further contribute to the study of its underlying molecular mechanism and targeted drugs." (PMID 37435030, 2023). "YEATS4 plays a role in the development and progression of many cancers, and its expression is involved in tumor cell proliferation, invasion, metastasis, epithelial-mesenchymal transition transformation, and treatment resistance." (PMID 37435030, 2023). "Further studies are needed to verify the potential interaction mechanisms between YEATS4 and other proteins in other cancers." (PMID 37435030, 2023). "Nevertheless, more effective small-molecule inhibitors targeting YEATS4 should be developed to provide opportunities for drug design for cancer therapy." (PMID 37435030, 2023). "Taken together, YEATS4 has emerged as a potential target for multiple cancers and is an attractive protein for the development of small-molecule inhibitors." (PMID 37435030, 2023). "This review aims to provide a comprehensive overview of the function and carcinogenic effects of YEATS4 and facilitate further exploration of therapeutic targets and prognostic biomarkers for various cancers." (PMID 37435030, 2023). "Our study demonstrated the effects of YEATS4 on the motility of cancer cells, suggesting the regulation of cell motility by YEATS4." (PMID 28445953, 2017). "Two other chromatin regulators, the chromatin reader Brd4 and histone acetyltransferase YEATS4, were also highly ranked as putative cancer driver genes." (PMID 24874471, 2014). "While the amplifications of SETDB1 and BRD4 have been previously identified and their roles in cancer have been well-studied, less is known about the functions of YEATS4 and NSD3 in cancer." (PMID 24874471, 2014). "Reduction of the YEATS4 protein upon KAT8 depletion might be a general mechanism as similar effects were observed in various cancer cell lines." (PMID 38526153, 2024). "Numerous studies have shown that YEATS4 is amplified during cancer progression." (PMID 37435030, 2023). "In contrast, the knockdown of YEATS4 was followed by the suppression of all typical features of tumor cells, suggesting that YEATS4 may be a potential therapeutic target and a prognostic biomarker for cancer." (PMID 37435030, 2023). "However, research on YEAST4 in tumor-related fields is limited and its biological functions, metabolism, and the regulatory mechanism of YEATS4 in numerous cancers remain undetermined." (PMID 37435030, 2023). "Based on the molecular mechanism of YEATS4’s role in cancer, the development of drugs targeting YEATS4 to inhibit its activity and function may exert an effect on cancer treatment." (PMID 37435030, 2023). "Although previous studies have reported the functions of YEATS4 in the cell growth and apoptosis, the roles of YEATS4 in the migration, invasion and metastasis of cancer cells remain unknown." (PMID 28445953, 2017).
cancer (continued). "YEATS4 (also known as GAS41) is a member of a large family of domain proteins which form complexes involved in chromatin modification and transcriptional regulation and has a strong link to cancer." (PMID 22144904, 2011). "We also find that we are able to successfully transfer our cancer models to tumour-adjacent tissue when inspecting the top 6 genes explained by CNVs (i.e. LLPH, YEATS4, UQCRFS1, POP4, CNOT2, and CAND1)." (PMID 40041206, 2025). "It is interesting that the rewiring of a metabolic pathway by YEATS4 amplification in NSCLC facilitates the intrinsic response to oxidative stress and further promotes cancer progression." (PMID 38514704, 2024). "Therefore, inhibiting the activity of YEATS4 might be a promising strategy for the cancer therapy." (PMID 28445953, 2017). "In particular, we identified the epigenetic regulatory genes NSD3, SETDB1, YEATS4, and BRD4 as putative amplified cancer drivers in several cancer types." (PMID 24874471, 2014). "The cancer driver signatures for SETDB1, YEATS4, NSD3, and BRD4 in TCGA datasets suggests that these genes are important cancer therapeutic targets and potential patient tailoring markers for epigenetics drug discovery efforts." (PMID 24874471, 2014). "Moreover, overexpression of YEATS4 in HPAC and Capan-1 cells improved the motility of cancer cells demonstrated by the cell migration assay and invasion assay." (PMID 28445953, 2017). "Obviously, the mRNA level of YEATS4 was significantly higher in cancer tissues when compared with the paired non-cancerous tissues." (PMID 28445953, 2017). "In contrast, the histone acetyltransferase YEATS4 displayed negative shRNA scores in a subset of cancer cell lines." (PMID 24874471, 2014).
tumor (18 papers, 2004 to 2025). "The locus 12q15 (lead SNP rs11177644) was associated with a pattern driven by two cis eQTLs, LYZ and YEATS4, and including 34 trans eQTLs, several of them tumor-related genes." (PMID 22144904, 2011). "Furthermore, immunohistochemical (IHC) staining of YEATS4 in 78 BC tumor tissues showed that YEATS4 was higher in tumor tissues than in adjacent normal tissues, and high YEATS4 protein levels were associated with shorter overall survival in BC patients." (PMID 38526153, 2024). "Yeats4 is a component of the NuA4 complex, which is involved in DNA repair, and Yeats4 deletion in tumor cells reduces the efficiency of DNA repair." (PMID 40707437, 2025). "YEATS4 knockdown effectively suppressed malignant tumor behaviors, highlighting its therapeutic potential." (PMID 40787449, 2025). "More importantly, disruption of YEATS4 acetylation inhibited tumor growth and sensitized BC cells to DDP." (PMID 38526153, 2024). "The findings reveal a critical role of the KAT8/YEATS4 axis in both tumor growth and cisplatin sensitivity in BC cells, potentially generating a novel therapeutic strategy for BC patients." (PMID 38526153, 2024). "Depletion of YEATS4 significantly reduced cell viability, colony formation, and tumor growth." (PMID 38526153, 2024). "Additionally, accumulating evidence indicates that the aberrant activation of YEATS4 leads to changes in drug resistance, epithelial-mesenchymal transition and also in the migration and invasion capacity of tumor cells." (PMID 37435030, 2023). "Therefore, specific inhibition of the expression or activity of YEATS4 protein may be an effective strategy for inhibiting the proliferation, motility, differentiation, and/or survival of tumor cells." (PMID 37435030, 2023). "Collectively, these experimental findings indicated that YEATS4 played an essential contributor in regulating the proliferation, migration and invasion of GBM cells, potentially promoting tumor malignancy through modulation of these key biological processes." (PMID 40787449, 2025). "In this study, we found that acetylation of YEATS4 by KAT8 promotes YEATS4 protein stabilization, which contributes to DNA repair and BC tumor growth." (PMID 38526153, 2024). "The co-amplification of HMGA2, TSPAN31, and YEATS4 with MDM2 is frequently observed in DDLPS and is involved in tumor development." (PMID 34834427, 2021). "M60 tumor exhibited two chromosome 12 loci resulting in high gene overexpression, including of MDM2, YEATS4 and FRS2." (PMID 33853673, 2021). "Specifically, in BC cells, KAT8‐mediated YEATS4 acetylation at K64, 65, and 69 promotes YEATS4 stabilization by blocking its HUWE1‐dependent degradation, which in turn contributes to DNA repair and tumor growth and consequently results in DDP resistance." (PMID 38526153, 2024). "Here, we demonstrate that acetylation of YEATS4 by the histone acetyltransferase KAT8 stabilizes YEATS4 via impairing its binding to E3 ligase HUWE1 and promotes BC tumor growth and that targeting the KAT8/YEATS4 axis suppresses tumor growth and sensitizes BC cells to cisplatin." (PMID 38526153, 2024). "Furthermore, we checked the protein levels of NOTCH2, YEATS4, HEY1, and HES6 in tumor tissues of the xenograft experiment." (PMID 29706630, 2018). "We found that the expression levels of NOTCH2, HEY1, and HES6 were lower in lncAKHE-silenced HCC cell-derived tumor tissues than in control tumor tissues, whereas YEATS4 expression was not affected." (PMID 29706630, 2018). "Inhibition of KAT8 by MG149 suppresses YEATS4 acetylation, leading to an increase in HUWE1 binding to YEATS4, and therefore facilitating HUWE1‐mediated YEATS4 ubiquitination and proteasomal degradation, which subsequently reduces DNA repair and tumor growth and enhances DDP sensitivity." (PMID 38526153, 2024). "However, according to the available experimental results, the molecular mechanisms of YEATS4 in different types of tumor cells are not the same." (PMID 37435030, 2023).
neurological diseases (1 paper, 2025). "Given that neuronal genome instability has been implicated in neurological diseases, dysfunction of a molecular network in which SBNO1 and YEATS4 are involved may contribute to disease pathogenesis." (PMID 40707437, 2025).
YEATS4 also shares sentences with these, for which no sentence is quoted: leukemia (3 papers); acute myeloid leukemia (1); Aphasia (1); astrocytoma (1); dysphasia (1); Huntington disease (1); infection (1); lung adenocarcinoma (1); melanoma (1); sarcoma (1); Uterine leiomyoma (1).